MRPS7 (mitochondrial ribosomal protein S7)
Synonyms: MRP-S7; S7mt; bMRP27a; MRP-S; RP-S7; RPMS7; uS7m; COXPD34
Tractability: Small molecule: a structure with a bound ligand is known. PROTAC: ubiquitination databases record sites on it; its protein half-life has been measured.
Target class: Other cytosolic protein
Gene: Protein-coding gene on chromosome 17 (75,261,670 to 75,270,708, forward strand). Ensembl gene ENSG00000125445.
Subcellular location: Mitochondrion
Subcellular location (Human Protein Atlas): Mitochondria
Pathways (Reactome):
Metabolism of proteins: Mitochondrial ribosome-associated quality control; Mitochondrial translation elongation; Mitochondrial translation initiation; Mitochondrial translation termination
Gene Ontology:
Molecular function: RNA binding; rRNA binding; structural constituent of ribosome
Biological process: mitochondrial translation; translation
Cellular component: mitochondrial small ribosomal subunit; mitochondrion; mitochondrial inner membrane; ribosome
Genetic constraint (gnomAD): Loss-of-function variants: 13 observed, 27.28 expected, observed/expected ratio (o/e) 0.48, 90% interval 0.31 to 0.76. The upper end of that interval is the gene's LOEUF score, 0.76, which puts it in group 3 of 6, group 1 being the genes least tolerant of losing a copy. Missense variants: 318 observed, 323.57 expected, observed/expected ratio (o/e) 0.98, 90% interval 0.9 to 1.08. Synonymous variants: 129 observed, 117.82 expected, observed/expected ratio (o/e) 1.09, 90% interval 0.95 to 1.27.
Gene-disease validity (ClinGen):
ClinGen rates the evidence that MRPS7 causes each of these diseases.
mitochondrial disease (autosomal recessive): Limited.
Homologues: Orthologues: macaque MRPS7 (94% identical), chimpanzee MRPS7 (92% identical), pig MRPS7 (88% identical), dog MRPS7 (86% identical), mouse Mrps7 (85% identical), rat Mrps7 (85% identical), guinea pig MRPS7 (81% identical), tropical clawed frog mrps7 (61% identical), zebrafish mrps7 (59% identical), Drosophila melanogaster mRpS7 (36% identical), Caenorhabditis elegans mrps-7 (31% identical). Paralogues in human: RPS5 (17% identical).
Diseases named in the same sentence as MRPS7 in open-access papers:
MRPS7 is named in the same sentence as 47 diseases in open-access papers, as found by Europe PMC text mining. Sharing a sentence is not in itself a finding about the gene and the disease. The quoted sentences say what the papers report.
breast carcinoma (9 papers, 2019 to 2026). "MRPS7 has been shown to be highly expressed in breast cancer, where it serves as a critical regulator of metabolic reprogramming in malignant cells." (PMID 41522354, 2026). "Moreover, MRPS7 was predominantly detected in epithelial breast cancer cells but was notably absent or minimally expressed in neighboring tumor stromal cells, which may participate the malignant progression of breast cancer." (PMID 41522354, 2026).
Perrault syndrome (3 papers, 2022 to 2025). Perrault syndrome (PS) is characterized by the association of ovarian dysgenesis in females with sensorineural hearing impairment. "Strikingly, a recent report identified a patient with the Perrault syndrome who possessed a compound heterozygous mutation (c.373A>T/p.K125stop, c.536G>A/p.R179H) in the MRPS7 gene." (PMID 37860580, 2023). "This second independent report validates that variants in MRPS7 are a cause of syndromic POI/Perrault syndrome." (PMID 36421788, 2022). "Variants in MRPS7 have been associated with clinical features overlapping Perrault syndrome." (PMID 39701103, 2025). "Another homozygous MRPS7 mutation (c.550A>G, p.M184V), found in two patients, resulted in sensorineural deafness combined with lactic acidemia, progressive renal and hepatic failure and, at least in one of them, primary hypogonadism; it was recently proposed to be reclassified as Perrault syndrome." (PMID 37860580, 2023).
osteosarcoma (2 papers, 2020). A usually aggressive malignant bone-forming mesenchymal neoplasm, predominantly affecting adolescents and young adults. "In this study, we have identified MRPS7 and MTIF2 as hub genes involved in the metastasis of osteosarcoma." (PMID 32665038, 2020). "Some of these genes have been reported as biomarkers for osteosarcoma, while the role of HLA-DRA, MTIF2, MRPS7 and CDK20, should also be further systematically investigated based on actual diseased tissues or even cell lines and animal models." (PMID 32665038, 2020). "Lately, MRPS7 was detected as a key gene in the pathophysiological process of osteosarcoma and the MRPL3 content is positively correlated with the prognosis of osteosarcoma." (PMID 33238645, 2020). "Therefore, protein synthesis involved in MRPS7 and MTIF2 within the mitochondrion might also have a potential connection with the development of osteosarcoma." (PMID 32665038, 2020).
AIDS (1 paper, 2015). A syndrome resulting from the acquired deficiency of cellular immunity caused by the human immunodeficiency virus (HIV). "Somewhat surprisingly, a lower transcription of MRPS10 but a higher transcription of MRPS7 are associated with slow and non-progression towards AIDS." (PMID 26367535, 2015).
congenital sensorineural deafness (1 paper, 2020). "Studies have confirmed that Mrps7 mutations could cause mitochondrial respiratory chain dysfunction and congenital sensorineural deafness." (PMID 32493433, 2020).
deafness (1 paper, 2025). An inherited or acquired condition characterized by the complete loss of the ability to hear from one or both ears. "Variants in the gene encoding 12S rRNA (MT-RNR1, MIM: 561000) are associated with sensorineural, non-syndromic deafness, suggesting that, as a result of their reduced abundance, altered MRPS7 and 12S rRNA interactions might account for the SNHL in individuals with variants in DAP3." (PMID 39701103, 2025).
hypogonadism (1 paper, 2023). A disorder characterized by decreased function of the gonads. "Homozygous variants in MRPS22 have been reported in non-syndromic POI patients, whereas variants in MRPS7 have been described in a patient with failure of pubertal development and hypogonadism, emphasizing the role of these genes in ovarian development." (PMID 37148394, 2023). "The other sister with a milder disease course, however, experienced failure of pubertal development and hypogonadism indicating the requirement of MRPS7 for reproductive function." (PMID 37148394, 2023).
kidney failure (1 paper, 2023). An acute or chronic condition that is characterized by the inability of the kidneys to adequately filter the blood. "For example, disruption to MRPS7 is known to result in POI, hearing loss and kidney failure." (PMID 37148394, 2023).
nasopharyngeal carcinoma (1 paper, 2026). A carcinoma arising from the nasopharyngeal epithelium. "Furthermore, to further validate the impact of MRPS7/MRPS23 knockdown on the stemness of nasopharyngeal carcinoma cells, we observed that knockdown of MRPS7 or MRPS23 markedly reduced the proportion of side population (SP) cells via flow cytometry." (PMID 41522354, 2026).
cancer (25 papers, 2017 to 2026). A tumor composed of atypical neoplastic, often pleomorphic cells that invade other tissues. "This suppression led to the inhibition of EMT and cancer stem cell properties, highlighting the cooperative role of MRPS7 and MRPS23 in NPC pathogenesis." (PMID 41522354, 2026). "Given the critical role of EMT and cancer stemness in mediating chemoresistance and metastatic dissemination, we sought to further elucidate the functional contributions of MRPS7 and MRPS23 to these clinically relevant phenotypes." (PMID 41522354, 2026). "Mechanistically, MRPS7/23 depletion destabilizes mitochondrial translation machinery, impairing DNA replication and inhibiting cancer stemness and EMT through suppression of β-catenin signaling." (PMID 41522354, 2026). "Compared with MRPS23, the functional role of MRPS7 in cancer remains poorly characterized." (PMID 41522354, 2026). "Strikingly, dual knockdown of MRPS7 and MRPS23 synergistically suppressed tumor growth by inhibiting β-catenin signaling, thereby attenuating EMT and cancer stemness." (PMID 41522354, 2026). "Here, our study reveals that MRPS7 and MRPS23 critically stabilize β-catenin by inhibiting its ubiquitination, thereby promoting β-catenin-mediated cancer stemness and EMT in NPC." (PMID 41522354, 2026). "Collectively, these findings position MRPS7 and MRPS23 as critical upstream modulators that orchestrate β-catenin-dependent control of two fundamental oncogenic programs in NPC: EMT progression and cancer stem cell maintenance." (PMID 41522354, 2026). "Collectively, our findings reveal that MRPS7 and MRPS23 serve as critical cooperative regulators in the progression of NPC progression, orchestrating a network of oncogenic processes that encompass cellular migration, EMT, and the maintenance of cancer stemness." (PMID 41522354, 2026).
tumor (12 papers, 2016 to 2026). "Using subcutaneous tumor xenografts, knockdown of MRPS7 and MRPS23 dramatically potentiated cisplatin efficacy, leading to substantial decreases in both tumor volume and mass in cisplatin-administered murine models." (PMID 41522354, 2026). "Results showed that knockdown of MRPS7 or MRPS23 alone significantly reduced tumor size and weight, while combined knockdown exerted a more pronounced inhibitory effect on tumor growth." (PMID 41522354, 2026). "Both tumor size and tumor-initiating capacity were significantly diminished in the MRPS7/MRPS23 knockdown groups." (PMID 41522354, 2026). "The specific difference in immune cell infiltration in the tumor microenvironment between patients with high and low expression of MRPS7 was explored." (PMID 36010978, 2022). "Genetic silencing of MRPS7/MRPS23 decreased tumor burden by 54.13% versus controls." (PMID 41522354, 2026). "However, the tumor-suppressive effects of MRPS7 downregulation remain poorly understood." (PMID 41522354, 2026). "Strikingly, dual knockdown of MRPS7 and MRPS23 resulted in synergistic anti-tumor effects, mediated through the suppression of β-catenin signaling." (PMID 41522354, 2026). "Our findings revealed that the knockdown of MRPS7 and MRPS23 synergistically enhanced the anti-tumor efficacy of cisplatin in NPC." (PMID 41522354, 2026). "We further observed that MRPS7 and MRPS23 are significantly overexpressed in NPC, and their suppression potentiates cisplatin's efficacy in inhibiting subcutaneous tumor growth and pulmonary metastasis in NPC xenograft models." (PMID 41522354, 2026). "To delineate the specific cell populations expressing MRPS7 and MRPS23 within the tumor microenvironment of NPC, we performed single-cell RNA sequencing (scRNA-seq) analysis using datasets NPC-GSE150430 and NPC-GSE162025 from the TISCH database." (PMID 41522354, 2026). "In summary, our study identifies MRPS7 and MRPS23 as pivotal oncogenic drivers that promote tumor growth, metastasis, and chemoresistance in NPC." (PMID 41522354, 2026). "The expression levels of two protective genes, MRPS7 and ORC1, were higher in normal tissues compared to tumor tissues." (PMID 41942958, 2026). "In this study, we demonstrated that dual knockdown of mitochondrial ribosomal proteins MRPS7 and MRPS23 not only exerts intrinsic anti-tumor effects but also synergizes with cisplatin to enhance therapeutic outcomes." (PMID 41522354, 2026). "In the meanwhile, we observed that both MRPS7 and MRPS23 were significantly overexpressed in NPC, further supporting their potential roles in promoting tumor progression across relevant malignancies." (PMID 41522354, 2026). "To delineate the role of MRPS7 and MRPS23 in promoting tumor progression and their potential functional interplay in NPC, we generated MRPS7 and MRPS23 single- and double-knockdown NPC cell lines in the Cne2 and C666 models." (PMID 41522354, 2026). "To further evaluate the clinical relevance of MRPS7 and MRPS23 in NPC, we performed IHC staining on tumor specimens from 41 patients who had received cisplatin (DDP)-based therapy." (PMID 41522354, 2026). "Collectively, these findings demonstrate that MRPS7 and MRPS23 function as tumor promoters in NPC, with combined knockdown exhibiting synergistic inhibition of tumor progression and metastasis in NPC." (PMID 41522354, 2026). "Knockdown of MRPS7 and MRPS23 not only suppresses tumor progression but also synergizes with cisplatin to enhance therapeutic efficacy." (PMID 41522354, 2026). "Here, our study revealed that knockdown expression of MRPS7 and MRPS23 exhibited an anti-tumor effect and have a synergistic effect with cisplatin, further investigation into the regulatory mechanisms revealed that USP10 acts as a key regulator of MRPS7 and MRPS23 expression." (PMID 41522354, 2026). "A significant upregulation of MRPS7, MRPS23, and USP10 was observed in tumor tissues relative to matched adjacent non-tumor tissues." (PMID 41522354, 2026).
tumor (continued). "Given that knockdown of USP10 reduced the expression of MRPS7 and MRPS23, and considering the lack of potent antagonists targeting MRPS7 and MRPS23 directly, we investigated spautin-1, a well-characterized USP10 inhibitor with demonstrated anti-tumor effects, as a potential therapeutic agent." (PMID 41522354, 2026).
mitochondrial disease (3 papers, 2017 to 2022). "Mitochondrial disease-causing mutations were found in thirteen small ribosomal subunit mitoribosomal proteins (MRPS1, MRPS2, MRPS6, MRPS7, MRPS9, MRPS11, MRPS14, MRPS16; MRPS22, MRPS23, MRPS25, MRPS34, MRPS39) and four large ribosomal mitochondrial proteins (MRPL3, MRPL12, MRPL24, MRPL44)." (PMID 36140315, 2022).
renal disease (1 paper, 2023). "Two siblings with a homozygous variant in MRPS7 (MIM: 611974) experienced liver and renal disease, which progressed to early death in one sister." (PMID 37148394, 2023).
MRPS7 also shares sentences with these, for which no sentence is quoted: metabolic disorders (5 papers); lung cancer (4); cardiovascular diseases (3); ovarian carcinoma (3); gastric cancer (2); neurodegenerative disease (2); aging (1); Alzheimer disease (1); Arthritis (1); cardiomyopathy (1); colorectal cancer (1); diffuse large B-cell lymphoma (1); glioblastoma (1); heart disease (1); hepatocellular carcinoma (1); hypertrophic cardiomyopathy (1); ischaemic stroke (1); lactic acidosis (1); Leigh syndrome (1); leukemia (1); liver cancer (1); lung adenocarcinoma (1); lung squamous cell carcinomas (1); lymph node metastasis (1); meningitis (1); metastatic cancer (1); microcephaly (1); muscle atrophy (1); Obesity (1); Ovarian Insufficiency (1).
A further 4 diseases each share a sentence with MRPS7 in 1 paper.